IGKV2-30 (immunoglobulin kappa variable 2-30)
Description:
V region of the variable domain of immunoglobulin light chains that participates in the antigen recognition. Immunoglobulins, also known as antibodies, are membrane-bound or secreted glycoproteins produced by B lymphocytes. In the recognition phase of humoral immunity, the membrane-bound immunoglobulins serve as receptors which, upon binding of a specific antigen, trigger the clonal expansion and differentiation of B lymphocytes into immunoglobulins-secreting plasma cells. Secreted immunoglobulins mediate the effector phase of humoral immunity, which results in the elimination of bound antigens. The antigen binding site is formed by the variable domain of one heavy chain, together with that of its associated light chain. Thus, each immunoglobulin has two antigen binding sites with remarkable affinity for a particular antigen. The variable domains are assembled by a process called V-(D)-J rearrangement and can then be subjected to somatic hypermutations which, after exposure to antigen and selection, allow affinity maturation for a particular antigen.
Synonyms: A17; IGKV230
Tractability: Antibody: its Gene Ontology location is reachable by antibodies, with high confidence; UniProt places it where antibodies can reach, with medium confidence; UniProt predicts a signal peptide or a membrane-spanning region. PROTAC: ubiquitination databases record sites on it.
Gene: Immunoglobulin variable (V) gene on chromosome 2 (89,244,781 to 89,245,596, reverse strand). Ensembl gene ENSG00000243238.
Subcellular location: Secreted; Cell membrane
Pathways (Reactome):
Immune System: Antigen activates B Cell Receptor (BCR) leading to generation of second messengers; CD22 mediated BCR regulation; Classical antibody-mediated complement activation; FCERI mediated Ca+2 mobilization; FCERI mediated MAPK activation; FCERI mediated NF-kB activation; FCGR activation; Fc epsilon receptor (FCERI) signaling; Immunoregulatory interactions between a Lymphoid and a non-Lymphoid cell; Initial triggering of complement; Regulation of Complement cascade; Regulation of actin dynamics for phagocytic cup formation; Role of LAT2/NTAL/LAB on calcium mobilization; Role of phospholipids in phagocytosis
Disease: FCGR3A-mediated IL10 synthesis; FCGR3A-mediated phagocytosis; Potential therapeutics for SARS
Hemostasis: Cell surface interactions at the vascular wall
Vesicle-mediated transport: Scavenging of heme from plasma
Gene Ontology:
Molecular function: antigen binding
Biological process: immune response
Cellular component: blood microparticle; extracellular exosome; extracellular region; immunoglobulin complex; plasma membrane
Homologues: Paralogues in human: IGKV2D-30 (99% identical), IGKV2-24 (88% identical), IGKV2D-24 (87% identical), IGKV2D-40 (82% identical), IGKV2-28 (82% identical), IGKV2D-28 (82% identical), IGKV2D-29 (81% identical), IGKV2D-26 (75% identical), IGKV2-40 (68% identical), IGKV3-20 (58% identical), IGKV4-1 (58% identical), IGKV3-11 (57% identical), and 81 more.